Y_RNA (Y RNA )
Gene: Miscellaneous RNA gene on chromosome 10 (103,673,158 to 103,673,265, forward strand). Ensembl gene ENSG00000222503.
Homologues: Orthologues: chimpanzee Y_RNA (98% identical), macaque Y_RNA (91% identical). Paralogues in human: Y_RNA (81% identical), Y_RNA (80% identical), RNY1 (79% identical), Y_RNA (79% identical), Y_RNA (78% identical), Y_RNA (77% identical), RNY1P7 (76% identical), Y_RNA (76% identical), RNY1P5 (75% identical), Y_RNA (75% identical), RNY1P11 (74% identical), Y_RNA (74% identical), and 95 more.